ARHGDIG (Rho GDP dissociation inhibitor gamma)
Description:
Inhibits GDP/GTP exchange reaction of RhoB. Interacts specifically with the GDP- and GTP-bound forms of post-translationally processed Rhob and Rhog proteins, both of which show a growth-regulated expression in mammalian cells. Stimulates the release of the GDP-bound but not the GTP-bound RhoB protein. Also inhibits the GDP/GTP exchange of RhoB but shows less ability to inhibit the dissociation of prebound GTP.
Synonyms: RHOGDI-3
Tractability: Antibody: its Gene Ontology location is reachable by antibodies, with high confidence.
Gene: Protein-coding gene on chromosome 16 (280,450 to 283,010, forward strand). Ensembl gene ENSG00000242173.
Subcellular location: Cytoplasm
Subcellular location (Human Protein Atlas): Cytosol; Plasma membrane
Pathways (Reactome):
Signal Transduction: CDC42 GTPase cycle; RHOB GTPase cycle; RHOG GTPase cycle; RHOH GTPase cycle
Gene Ontology:
Molecular function: protein binding; Rho GDP-dissociation inhibitor activity; GDP-dissociation inhibitor activity; GTPase regulator activity
Biological process: negative regulation of cell adhesion; Rho protein signal transduction
Cellular component: cytosol; cytoplasmic vesicle; membrane; cytoplasm
Genetic constraint (gnomAD): Loss-of-function variants: 18 observed, 20.58 expected, observed/expected ratio (o/e) 0.87, 90% interval 0.6 to 1.3. The synonymous counts are far from expectation, so gnomAD's model fits this gene poorly and the ratio says little. Missense variants: 311 observed, 285.5 expected, observed/expected ratio (o/e) 1.09, 90% interval 0.99 to 1.2. Synonymous variants: 193 observed, 127.77 expected, observed/expected ratio (o/e) 1.51, 90% interval 1.34 to 1.7.
Homologues: Orthologues: chimpanzee ARHGDIG (98% identical), macaque ARHGDIG (98% identical), pig ARHGDIG (86% identical), dog ARHGDIG (84% identical), guinea pig ARHGDIG (83% identical), rat Arhgdig (82% identical), mouse Arhgdig (80% identical), zebrafish arhgdig (54% identical), Drosophila melanogaster RhoGDI (40% identical), Caenorhabditis elegans rhi-1 (32% identical). Paralogues in human: ARHGDIA (53% identical), ARHGDIB (50% identical).
Diseases named in the same sentence as ARHGDIG in open-access papers:
ARHGDIG is named in the same sentence as 9 diseases in open-access papers, as found by Europe PMC text mining. Sharing a sentence is not in itself a finding about the gene and the disease. The quoted sentences say what the papers report.
lung carcinoma (1 paper, 2022). "We picked the top 5 genes (ZNF24, NR3C2, CST4, ARHGDIG and CRYBB3) to confirm their lung cancer suppressive function." (PMID 36457047, 2022).
tumor (3 papers, 2016 to 2025). "The highly expressed ARHGDIG in the KLF‐P group leads to a poor prognosis of PCa (P = .00028), and the expression of ARHGDIG in tumours is negatively associated with the KLF5 levels (R = −0.34, P < .001), confirming the prognostic value of KLF5 in PCa." (PMID 32281273, 2020). "Moreover, mRNA expressions of CA14, RPE65, IGSF1, SLC18 A2 and CPNE6 were significantly lower in PCa samples compared to benign samples, while HJURP, COMP, KRTAP5-1, VGF, SSTR1, LINC01612, NAALADL2-AS2, AMH and ARHGDIG were elevated in tumor samples (p < 0.05)." (PMID 40592939, 2025).
cancer (2 papers, 2016 to 2021). A tumor composed of atypical neoplastic, often pleomorphic cells that invade other tissues. "Out of those four genes, three (RHOC, LZTS1, ARHGDIG) are known cancer genes." (PMID 34762640, 2021).
cardiovascular disease (1 paper, 2022). "The role of other genes such as NARS, PKDCC, ARHGDIG, STARD10, and MAPK12 expressed in the hypertrophy stage requires more investigation in cardiovascular disease." (PMID 35625658, 2022).
ARHGDIG also shares sentences with these, for which no sentence is quoted: basophilic leukemia (1 paper); breast carcinoma (1); hepatocellular carcinoma (1); mood disorder (1); pancreatic cancer (1).